ACHE (acetylcholinesterase (Yt blood group))
Diseases named in the same sentence as ACHE in open-access papers (continued):
Sharing a sentence is not in itself a finding about the gene and the disease.
Cognitive impairment (continued). "Given the critical role of AChE in regulating acetylcholine (ACh) balance and synaptic neurotransmission, the inhibition of AChE activity by these agents suggests their potential to ameliorate cognitive impairment observed in this study." (PMID 40827097, 2025). "For the in vivo component, scopolamine-induced cognitive impairment—characterized by muscarinic receptor blockade, elevated hippocampal and cortical AChE activity, and reduced ACh availability—was selected to replicate central cholinergic deficiency, a fundamental AD pathological feature." (PMID 41007261, 2025). "Oleamide is a documented neuroactive fatty-acid amide that reverses scopolamine-induced cognitive impairment and restores cholinergic function, which aligns with its moderate docking to ACHE/CHRM1 in our dataset and the enrichment of synaptic receptor pathways." (PMID 41440909, 2025). "Acetylcholinesterase (AChE) inhibitors are employed for patients with mild cognitive impairment or mild dementia stage disease (stage 4 based on FDA classification) to impede ACh degradation and, in turn, boost neural cell function by increasing ACh levels (Akıncıoğlu and Gülçin, 2020)." (PMID 39185459, 2024). "However, in the same model of sepsis we have previously shown that sepsis significantly increases AChE activity one‐month after sepsis induction along with significant cognitive impairment." (PMID 39370294, 2024). "Our findings suggest that the increased activities of AChE and MAO in the cerebral cortex of diabetic rats may contribute to the cognitive impairment that is associated with this condition." (PMID 38683825, 2024). "Reduces cognitive impairment; reverses AChE activity, GPX activity, NO metabolites, and ROS levels." (PMID 39149548, 2024). "AChE inhibitors are the first-line medicine in PD patients with cognitive deficits." (PMID 39627827, 2024). "In addition to AChE and COX-2, molecular docking was also performed on other molecular targets linked to cognitive impairment, including GSK-3β, BACE-1, and caspase-3." (PMID 39598743, 2024). "In addition to the role it plays as an AChE inhibitor, donepezil has been reported to improve cognitive impairment via the following mechanisms: First, donepezil reduces mitochondrial amyloid-β (Aβ) accumulation and mitochondrial dysfunction." (PMID 39063593, 2024). "Elevated AChE activity, often observed in epilepsy, disrupts cholinergic signaling by accelerating acetylcholine hydrolysis, leading to increased neuronal excitability and cognitive impairments such as memory and learning deficits." (PMID 39911825, 2024). "However, cognitive impairment persisted even after the AChE activity was restored to control levels 21 days after the last exposure." (PMID 37106826, 2023). "The result suggests the sevoflurane improved the cognitive impairment after the isoflurane treatment may be involved in the activity of Ach, ChAT and AchE." (PMID 38055394, 2023). "In order to clarify the potential mechanisms that could impact cognitive impairment in scopolamine mice, the effect of drug therapy on AChE activity was investigated." (PMID 38004485, 2023). "Overexpression of human AChE in transgenic mice leads to cognitive impairment." (PMID 37153798, 2023). "Also, HMC improved cognitive deficits in rats through enhancing cholinergic effects, inhibiting AChE, β-secretase, and caspase-3." (PMID 37465125, 2023). "Moreover, in Alzheimer's disease rats induced by aluminum chloride, black tea extract significantly improved cognitive deficits while decreasing the activity of (AChE) acetylcholinesterase." (PMID 37324903, 2023). "Therefore, the current research on AD is mainly centered around the therapeutic approach of inhibiting AChE to address memory and cognitive impairment." (PMID 37999229, 2023).
Cognitive impairment (continued). "Six weeks of treatment with AlCl3 caused nitrosative oxide stress (lipid peroxidation), cognitive impairment, an increase in proinflammatory cytokines (IL-1beta and TNF-alpha) and increased AChE activity and reduced the BDNF content in the hippocampus of animals." (PMID 36829840, 2023). "It proved that rosinidin possesses AchE inhibitory activity, which is due to the antioxidant potentiality that elevated the oxidative defense mechanism of the cholinergic neurons and thus ameliorated behavioral and cognitive deficits." (PMID 35893108, 2022). "The Y-maze test found that glycyrrhizic acid could significantly improve the mice cognitive impairment induced by scopolamine, decrease AChE activity, and increase SOD and CAT activity." (PMID 35721142, 2022). "A significant elevation in AChE levels after DOX administration suggested that defective cholinergic activity due to neuroinflammation might be responsible for cognitive impairment in the experimental animals." (PMID 36364190, 2022). "On the other side, excessive AChE activity may result in a shortage of ACh and cognitive impairment." (PMID 36355133, 2022). "In addition, the authors verified that, while the cognitive impairment and the AChE activity were improved with drug solution and drug-loaded liposomes, rivastigmine incorporation into NPs achieved a more pronounced effect." (PMID 36365114, 2022). "Thus, AChE inhibitors with dual binding sites will not only stimulate the cholinergic system to alleviate cognitive deficits in AD patients, but also inhibit the production or aggregation of Aβ." (PMID 35968601, 2022). "In addition, cornuside isolated from C. fructus ameliorated cognitive impairment by increasing ACh level and ChAT activity and decreasing AChE activity in scopolamine-induced AD mice." (PMID 36613533, 2022). "However, TRF (60 and 120 mg/kg) treatments in T2DM rats attenuated the increased AChE activity and improved the cholinergic functioning, and protected the cognitive impairment, perhaps by inhibiting AChE activity and increasing ACh concentration." (PMID 36362316, 2022). "Therefore, the AChE is also one of the main therapeutic targets in AD, because its inhibition increases ACh levels and thus retards cognitive deficit." (PMID 35657793, 2022). "Topographic reductions in FEOBV binding correlated with domain-specific cognitive impairment, which is in line with the current literature reporting strong correlations between regional AChE activity and various neuropsychological measures for different cognitive functions." (PMID 35344804, 2022). "Additionally, simvastatin, ST09 (a novel thioester derivative of 6-chloro-tacrine), and the co-administration of melatonin and resveratrol significantly decrease AChE activity and rescue cognitive deficits in VaD rats." (PMID 33532143, 2021). "Therefore, PMG, leads to the increase of ACh availability and the stimulation of ERK by reducing the level of AChE, suppressing inflammation and thus improving cognitive deficits." (PMID 34577171, 2021). "Furthermore, the plant has been shown to inhibit AChE and protect against cognitive impairment in rats." (PMID 34541370, 2021). "Low AChE levels in the cerebral cortex of PD patients without dementia are strongly associated with cognitive impairment, which correlates simultaneously with cholinergic degeneration." (PMID 34502198, 2021). "However, less is known regarding the levels of the ACh-synthesizing enzyme ChAT and the ACh-degrading enzyme AChE in CSF and plasma in patients with cognitive impairment." (PMID 34512307, 2021). "In addition, we found that the antioxidant properties of the LS are well correlated with improved memory and anti-AChE abilities in a SCOP-induced zebrafish model of cognitive impairment." (PMID 34198639, 2021). "Furthermore, the reduction of AChE activity in cholinergic neurons is also involved with cognitive impairment as detected in Alzheimer’s disease." (PMID 33767223, 2021).
Cognitive impairment (continued). "Progressive cognitive impairment is also related to dynamic changes in ACh and AChE activity." (PMID 34336115, 2021). "In the AD hypothesis, these neurotransmitters decrease as a result of overexpression of AChE and BChE, leading to cognitive impairment." (PMID 32887386, 2020). "In addition, anti-AChE compounds can protect cells from neuronal death and cognitive impairment in neurodegenerative diseases." (PMID 32549266, 2020). "Phytoconstituents are used to treat cognitive disorders such as AD, Dementia and Parkinson’s disease through different approaches including acetylcholinesterase (AChE) inhibition, enhancement of cholinergic activity in CNS, anti-inflammatory, antioxidant and estrogen replacement therapy." (PMID 32332809, 2020). "Due to the increasing knowledge about the role of cholinergic transmission in sepsis, neuroinflammation and concomitant cognitive disorders, this study investigated whether AChE-activity is altered in septic patients with SAE/delirium." (PMID 33203376, 2020). "In addition, SCO treatment significantly decreased Ach levels and expression of ChAT protein while increasing AChE activity in both the hippocampus and cortex, suggesting that the observed cognitive impairments were induced by cholinergic dysfunction." (PMID 31141948, 2019). "Thus, we used scopolamine (2 mg/kg of animal b.w) to induce AD-like cognitive impairment in mice, and we also used Tac (10 mg/kg of animal b.w), an approved AChE inhibitor, as positive control." (PMID 29740000, 2018). "Therapeutic interventions aiming to alleviate cognitive impairments have thus targeted ACh regulation and degradation; acetylcholinesterase (AChE) inhibitors blocking ACh hydrolysis have been administered to treat amnesia and are widely prescribed to alleviate general cognitive decline." (PMID 29716575, 2018). "In current study, we find that SCOP decreases ACh content and ChAT activity, increases activity of AChE in both hippocampus and cortex, which indicate that the dysfunction of cholinergic nervous system might facilitate the process of cognitive impairment." (PMID 28852153, 2017). "Also, we measured AChE activity to investigate the relation between cognitive deficits and BDNF/CREB signaling cascades." (PMID 28817076, 2017). "AChE plays a vital role in the hydrolysis of the ACh neurotransmitter, which was found to be decreased in hippocampal and cortical levels of AD patients, resulting in cognitive impairment." (PMID 28792471, 2017). "Therefore, it is rational to expect that a higher concentration of fucoxanthin than that of donepezil is needed to reverse AChE-involved scopolamine-induced cognitive impairments in vivo." (PMID 27023569, 2016). "Moreover, AChE activity was proven to increase in diabetic models, which indicates alteration in the cholinergic neurotransmission with the consequent cognitive impairments observed in the diabetic state." (PMID 26262991, 2015). "The antioxidant effect of vildagliptin can clarify, in part, the decreased AChE in brain, where it was reported previously that some antioxidants, such as curcumin and vitamin E prevented the cognitive deficits induced by the diabetic state through the inhibition of AChE." (PMID 26262991, 2015). "Notably, SCH improved neuronal morphology and reduced AChE activity in cognitive impairment models." (PMID 40509464, 2025). "Thus, the synergistic effects of AChE inhibitors and war-related stress on cholinergic neurotransmission may be especially relevant to the cognitive deficits observed in GWI." (PMID 38919622, 2024). "AchE inhibitors may reduce the symptoms of cognitive deficits." (PMID 39046524, 2024). "Given that AChE inhibitors are the first-line treatment for cognitive disorders, dementia, and AD, Co-Q10, which has minimal side effects, could be a promising alternative to traditional drugs that are associated with undesirable side effects such as nausea, diarrhea, and appetite loss." (PMID 40066120, 2024).
Cognitive impairment (continued). "The current research was designed to examine whether a novel (-)-meptazinol-serotonin hybrid (Mep-S) with potent antioxidant activity and additional inhibitory properties for acetylcholinesterase (AChE) activity could attenuate oxidative neuronal damage and cognitive deficits." (PMID 36819782, 2023). "However, some evidence has shown that cognitive impairment persists long after repeated low-level exposure to OPs, although AChE activity is restored to normal, so this persistent impairment may be independent of AChE inhibition." (PMID 37106826, 2023). "Hence, inhibition of AChE and BChE activities and stimulation of Na+/K+-ATPase activity by tested extracts can provide an avenue for the development of effective drugs of plant origin for the management of cognitive disorders." (PMID 37006627, 2023). "Unexpectedly, SCOP, which was used in our study to induce cognitive impairment in zebrafish, showed AChE inhibition in 168 hpf larvae, possibly mediated via the anionic subsite of the catalytic center and the peripheral anionic site, as indicated by docking studies with human AChE." (PMID 35212831, 2022). "Therefore, antioxidants and AChE-inhibiting properties of PBE may contribute to cognition-enhancing effects in SCOP-induced cognitively impaired SD rats." (PMID 36552705, 2022). "Although donepezil is well known as the AchE inhibitor, evidence from animals, and humans showed donepezil could also enhance the NE level in cognitive impairments." (PMID 35281906, 2022). "Therefore, IR3G and IR might be considered as possible candidates to ameliorate PD, particularly the cognitive deficit or dementia in PD patients, via modulation of AChE." (PMID 35270118, 2022). "Since scopolamine has been used in the standard cognitive impairment model, there were a lot of literatures to show that the effects of scopolamine treatment can induce cognitive deficit through decreasing ACh contents and ChAT activities while increasing AChE activities in the hippocampus." (PMID 34073796, 2021). "Importantly, hypoxia has been shown to induce cognitive impairments and morphological damage in the rodent hippocampus in vivo, accompanied by increased AChE expression, while the administration of AChE inhibitors was able to alleviate hypoxia-induced cognitive impairments and neurodegeneration." (PMID 34359879, 2021). "Thus, SYR may not have a modulatory effect on AChE activity in diabetic conditions, while other phenolic acids (chlorogenic acid) reduced AChE in the hippocampus of the rats with cognitive deficits induced by intracerebroventricular STZ." (PMID 33457416, 2020). "Therefore, the attenuation of scopolamine-induced cognitive deficit by glyceollins could be mediated through activation of the Nrf2 signaling pathway as well as the inhibition of AChE." (PMID 29337893, 2018). "Therefore, it is likely that multi-functional molecules, such as bis(heptyl)-cognitin, which target AChE and Aβ oligomers simultaneously might not only minimize cholinergic dysfunction but also reverse the cognitive impairments in AD." (PMID 26194093, 2015). "Thus, modulation of the cholinergic signaling pathway, such as inhibition of AChE, activation of ChAT, and promotion of ACh synthesis, may serve as strategies for the treatment of memory dysfunction due to AD or poststroke cognitive impairments." (PMID 24194776, 2013). "Ergosterol directly inhibited AChE activity in vitro and was subsequently evaluated in vivo using a trimethyltin chloride (TMT)-induced mouse model of cognitive impairment." (PMID 41948388, 2026). "AFB1 alters the activity of key enzymes such as acetylcholinesterase (AChE) and monoamine oxidase (MAO), contributing to cholinergic dysfunction and cognitive impairment." (PMID 40943180, 2025). "Given this, our study sought to investigate how subchronic HgCl2 exposure interacts with type 2 diabetes to influence AChE activity and BDNF levels, potentially aggravating cognitive deficits." (PMID 40726602, 2025).
Cognitive impairment (continued). "In case of medical therapy, choices are narrow and many medications for AD belong to Acetylcholinesterase (AChE) inhibitors namely rivastigmine and donepezil (DON), showing promising effect in improving memory performance and cognitive impairment in patients." (PMID 37476485, 2023). "essential oil from the aerial parts and to evaluate its anxiolytic, promnesic, anti-AChE and antioxidant potential in a SCOP-induced zebrafish model of cognitive impairment." (PMID 36840131, 2023). "To further elucidate the effect of BTL-I on AlCl3-induced cognitive impairment in zebrafish, we assessed changes in the levels of several biochemical indicators (including IL-1β, TNF-α, GSH, AChE)." (PMID 35130930, 2022). "In addition to AChE inhibitory activity, AP5 can suppress neuroinflammation by regulating microglia and astrocyte phenotype transition, which may account for the rescue of neuron and synapse loss, and also cognitive deficits." (PMID 35860673, 2022). "Similar to these results, doses of pine stem bark extract significantly reduced the activity of AChE and improved ACh levels in STZ-induced Alzheimer's-type neurodegeneration and cognitive deficits." (PMID 36039041, 2022). "The results of the target-component network analysis showed that ADRB2, ADRA1B, DPP4, ACHE and ADRA1D played a key role in the treatment of mild cognitive impairment." (PMID 35646138, 2022). "Currently, the AChE inhibitors like donepezil, galantamine and rivastigmine, are the only FDA- and EMA-approved drugs for the symptomatic treatment of mild to moderate cognitive impairments." (PMID 33916760, 2021). "The present study analyzed the effect of 10% hexane solvent on Bean-PS-attenuated TMT-induced cognitive defects in the Morris water maze, and found a protective effect in contrast to TMT-induced reduction in ChAT and AchE in the hippocampal areas." (PMID 32664537, 2020). "Rats administered with D-gal/AlCl3 exhibited cognitive deficits, decreased activities of SOD, and marked increase in AChE and MDA levels." (PMID 30935005, 2019). "The optimal compound 19, 27, and 30 (human AChE IC50 = 10.2 ± 1.2, 16.5 ± 1.7, and 15.3 ± 1.8 nM, respectively) show good performance in ameliorating the scopolamine-induced cognition impairment and preliminary safety in hepatotoxicity evaluation." (PMID 29278947, 2018). "Implementing VNS and AChE inhibitors alone or in combination with other hearing rehabilitative interventions during the optimal time window may lead to greater disease-modifying benefits in the treatment of presbycusis-related tinnitus with cognitive impairment." (PMID 29681847, 2018). "Besides the facts that memory impairment induced by scopolamine is a result of an increase in AChE activity and brain oxidative status, it can be also assumed that scopolamine impairs neurogenesis in the brain which in turn leads to cognitive deficits as in AD." (PMID 29209218, 2017). "In addition, treatment with resveratrol was able to prevent the increase in AChE activity and consequently in cognitive impairment in diabetic rats, which meant that this polyphenol could modulate cholinergic neurotransmission and consequently improve cognition." (PMID 25525597, 2014). "Together, these results support a model in which CKDB001 alleviates cognitive impairment not by direct AChE inhibition, but by targeting upstream microbiota–metabolite–host signaling networks." (PMID 41465235, 2025). "However, due to the limitations of AChE inhibitors, including dosage constraints and inadequate long-term efficacy, BChE inhibitors are emerging as a new therapeutic target, suggesting that inhibiting BChE could be a potential therapeutic approach for cognitive impairments in SZ, BPD, and MDD." (PMID 40002349, 2025).